TOX (thymocyte selection associated high mobility group box)
Diseases named in the same sentence as TOX in open-access papers (continued):
Sharing a sentence is not in itself a finding about the gene and the disease.
ovarian carcinoma (3 papers, 2020 to 2025). A malignant neoplasm originating from the surface ovarian epithelium. "Further studies are needed to clarify the underlying mechanism that how TOX can affect the function of T cell and tumor cell in ovarian cancer microenvironment." (PMID 36434543, 2022). "In addition, a multivariate Cox model also suggested that TOX expression was an independent risk factor for OS in patients with ovarian cancer (Hazard Ratio = 2.255, 95%CI = 1.199–4.241, p*<0.05)." (PMID 36434543, 2022). "The results found that TOX was a potential prognosis-related biomarker in ovarian cancer and provided novel direction to understand the interactions between TOX expression, tumor infiltration, and T cells exhaustion." (PMID 36434543, 2022). "In this study, we comprehensively investigated the expression characteristics and prognostic value of the TOX in ovarian cancer." (PMID 36434543, 2022). "Survival analysis revealed that ovarian cancer patients with high TOX expression score generally shorter overall survival and disease-free survival times." (PMID 36434543, 2022). "Nevertheless, the correlations between TOX and prognosis in different types of cancer including ovarian cancer remain elusive." (PMID 36434543, 2022). "The Survival analysis and a Cox regression model were employed to identify the correlation between TOX expression and ovarian cancer patients’ survival rate." (PMID 36434543, 2022). "In this work, we found that TOX expression in ovarian cancer specimens resected from 116 patients by IHC." (PMID 36434543, 2022). "Besides, the expression of TOX was an independent predictor for ovarian cancer patients by multivariate Cox model analysis." (PMID 39758401, 2025). "Thus, we demonstrated TOX was a potential prognosis-related biomarker in ovarian cancer and suggested a new direction to understand the correlations between TOX, immune infiltration and T cells function in tumor microenvironment." (PMID 36434543, 2022). "In conclusion, we identified the expression of TOX in 116 patients with ovarian cancer and confirmed that the TOX could independently predicted poor survival and prognosis." (PMID 36434543, 2022). "We sought to understand the localization of TOX in the ovarian cancer milieu." (PMID 36434543, 2022). "TOX expression in ovarian cancer could be a promising tool for predict overall survival of ovarian cancer patients." (PMID 36434543, 2022). "We hope that detecting TOX expression in ovarian cancer may provide a new biomarker in guiding the treatment strategy for ovarian cancer." (PMID 36434543, 2022). "Univariate and Multivariate Cox demonstrated that TOX expression score could be used as an independent prognostic factor for patients with ovarian cancer." (PMID 36434543, 2022). "Here, we aimed to study the prognostic role of TOX in ovarian cancer." (PMID 36434543, 2022). "Importantly, we found that high TOX expression predicted poor OS and DFS in patients with ovarian cancer." (PMID 36434543, 2022). "However, the relationship between TOX expression and prognosis in ovarian cancer has not been comprehensively investigated." (PMID 36434543, 2022). "The impact of TOX expression is not detected on OS or PFS of gastric cancer or ovarian cancer." (PMID 32700817, 2020).
autoimmune conditions (2 papers, 2017 to 2021). "Novel gene-longevity associations included genes MICA/B (a locus previously linked to autoimmune conditions rheumatoid arthritis and multiple sclerosis), TOX, ZW10, SEMA6D, EGLN2/CYP2A6, EXOC3L2/MARK4 and C20orf187." (PMID 29227965, 2017). "We next determined the differential contribution of TOX for T-cell differentiation in acute infection and in CNS autoimmunity." (PMID 33579927, 2021). "Unsupervised clustering analysis identified five distinct modules of TOX-dependent epigenetic changes based on whether they were unique to CNS autoimmunity, unique to acute infection or equally found in the two settings." (PMID 33579927, 2021).
bladder cancer (2 papers, 2020 to 2023). "Variations in TOX expression in CTLs in bladder cancer patients result in radically different responses toward anti-PD-1 and TIGIT inhibitors." (PMID 36969216, 2023).
breast tumors (2 papers, 2012 to 2025). "In a genome-wide comparison of DNA methylation, the promoter CpG island of TOX is highly methylated in 43 % of breast tumors, while it is unmethylated in distant normal breast tissue." (PMID 39758401, 2025). "Among primary tumors, TOX and TOX3 were methylated in 5% (9/190) and 58% (110/190) lung and 43% (34/80) and 30% (24/80) breast tumors, respectively." (PMID 22496870, 2012). "Tumor-specific hypermethylation of TOX in breast tumors but not in the adjacent normal tissue has been recently demonstrated as a potential novel tumor biomarker." (PMID 22496870, 2012).
Burkitt lymphoma (2 papers, 2020 to 2021). A rare form of malignant mature B-cell non-Hodgkin lymphoma. "Further studies are required to elucidate the role played by TOX in Burkitt lymphomas." (PMID 32106280, 2020).
endothelial dysfunction (2 papers, 2019 to 2025). In vascular diseases, endothelial dysfunction is a systemic pathological state of the endothelium (the inner lining of blood vessels) and can be broadly defined as an imbalance between vasodilating and vasoconstricting substances produced by (or acting on) the endothelium. "However, the causal chain connecting TOX signaling to macrophage polarization, endothelial dysfunction, and tissue scarring remains incompletely defined." (PMID 41410848, 2025). "In this study, we determined the roles of the MALAT1/miR-181b/TOX signaling pathway in the setting of AS in cases of oxLDL-induced endothelial dysfunction." (PMID 31949884, 2019). "We presented the interactions among MALAT1, TOX, and miR-181b in oxLDL-induced endothelial dysfunction." (PMID 31949884, 2019). "If correct, interrupting TOX–RAGE signaling could simultaneously blunt endothelial dysfunction, macrophage activation, and fibroblast remodeling, and such approach could be potentially useful for preventing progression or treating early-stage fibrotic symptoms." (PMID 41410848, 2025).
glioma (2 papers, 2020 to 2023). A benign or malignant brain and spinal cord tumor that arises from glial cells (astrocytes, oligodendrocytes, ependymal cells). "Altogether, our data reveal that high expression of TOX is associated with reduced infiltration of immune cells in the microenvironment of gliomas." (PMID 32762688, 2020). "Compared to normal brain tissue, tumor samples demonstrated significantly up-regulated TOX expression, suggesting an association with glioma development." (PMID 32762688, 2020). "TOX is closely associated with the immune environment surrounding tumors, but its role in gliomas is not fully understood." (PMID 32762688, 2020). "Moreover, high expression of TOX was associated with better survival in pan-glioma analysis, LGG alone, and GBM alone." (PMID 32762688, 2020). "TOX was found to be highly elevated in gliomas based on its mRNA expression levels, especially in LGG." (PMID 32762688, 2020). "We further investigated the potential immune-related functions of TOX in glioma using GSVA analysis in TCGA dataset." (PMID 32762688, 2020). "TOX was up-regulated in MGMT promotor methylated glioma, glioma with IDH mutation, and glioma with 1p/19q codeletion." (PMID 32762688, 2020). "We obtained data from publicly available data-bases (TCGA, n = 674; CGGA, n = 1017) to evaluate the mRNA expression levels of TOX in WHO grade I-IV gliomas." (PMID 32762688, 2020). "TOX was down-regulated in malignant gliomas compared to low grade gliomas, and upregulated in the proneural and IDH mutant subtypes of GBM." (PMID 32762688, 2020). "All these results indicate that TOX expression occures in the wake of the glioma, and that TOX is critical in suppressing the oncogenic process and progression in this context." (PMID 32762688, 2020). "TOX expression is significantly reduced in high-grade gliomas compared with low-grade gliomas." (PMID 38275375, 2023). "Taken together, this study illuminates the role that TOX plays in the development of human gliomas." (PMID 32762688, 2020). "In addition, frequently observed mutations to EGFR (27%), IDH1 (20%), PTEN (18%), and MUC16 (16%) were present in gliomas with low TOX expression (n = 158)." (PMID 32762688, 2020). "Notably, the negative relation with lymphocyte migration and lymphocyte chemotaxis indicates that TOX is inclined to prohibit the formation of an immune infiltrating environment conducive to glioma." (PMID 32762688, 2020). "We further investigated the prognostic value of TOX in human gliomas." (PMID 32762688, 2020). "First, we evaluated TOX levels in various common cancer types including gliomas." (PMID 32762688, 2020). "Additionally, TOX was up-regulated with 1p/19q codeletion in pan-glioma analysis in both TCGA and CGGA cohorts." (PMID 32762688, 2020). "TOX expression was negatively associated with inflammatory activity signatures including HCK, LCK, MHC-I, MHC-II, STAT1, and interferon metagenes, but positively associated with the IgG metagene in pan-glioma analysis, LGG alone, and GBM alone." (PMID 32762688, 2020). "However, TOX might interact with B lymphocytes in the processes of immune-activation and subsequent glioma suppression." (PMID 32762688, 2020). "TFH (follicular helper cells) and tumor growth delay (TGD) were positively associated with TOX in the pan-glioma analysis and the LGG group, while TFH and B cells were positively associated with TOX, and macrophages and DCs were negatively associated with TOX in GBM samples." (PMID 32762688, 2020). "In the TCGA dataset, lower TOX expression was seen in MES and CL subtypes of GBM compared to NE and PN subtypes, while the distinction was conspicuous in pan-glioma analysis." (PMID 32762688, 2020). "Furthermore, in WHO grade II glioma samples, the IDH mutant tumors had the highest expression of TOX in both TCGA and CGGA cohorts." (PMID 32762688, 2020). "To date, TOX expression has not been fully characterized in gliomas." (PMID 32762688, 2020).
head and neck squamous cell carcinoma (2 papers, 2020). A squamous cell carcinoma that arises from any of the following anatomic sites: lip and oral cavity, nasal cavity, paranasal sinuses, pharynx, larynx, and salivary glands. "Only a few of cancer types, CHOL (cholangio carcinoma) and HNSC (head and neck squamous cell carcinoma), upregulated TOX expression in tumor tissues." (PMID 32700817, 2020).
peripheral T cell lymphoma (2 papers, 2019 to 2022). "In an L-HES patient who progressed to peripheral T cell lymphoma, the malignant transformation identified increases in the expression of CDCA7, TIGIT, and TOX, which are highly expressed in SS, suggesting that these genes contribute to neoplastic transformation." (PMID 31489115, 2019).
pulmonary tuberculosis (2 papers, 2014 to 2016). A bacterial infection that affects the lungs and is caused by Mycobacterium tuberculosis. "Age‐dependent association between pulmonary tuberculosis and common TOX variants in the 8q12‐13 linkage region." (PMID 27896281, 2016). "Similarly, previous studies have reported an age-dependent association between pulmonary tuberculosis and SNPs in genes including IFNGR2, TOX and NRAMP1." (PMID 25360588, 2014).
schizophrenia (2 papers, 2017 to 2023). A major psychotic disorder characterized by abnormalities in the perception or expression of reality. "The thymocyte selection associated high mobility group box gene (TOX) has an important role in regulating neural stem cell proliferation in neural tissues, and differential expression was seen between patients with schizophrenia and control patients (accuracy of 86%)." (PMID 36658485, 2023). "In Conclusion, our findings suggest the role of TOX, ADIPOQ and BDNF in weight and WHR gain induced by atypical antipsychotics in schizophrenia subjects." (PMID 28327672, 2017).
T-cell lymphoma (2 papers, 2020 to 2021). "In T-cell lymphomas high TOX expression was found in all the MF (100%), in precursor T lymphoblastic lymphoma (71%) and in a high percentage of AITL (83%) while PTCL and ALCL were mainly negative." (PMID 32106280, 2020). "In T-cell lymphomas, high TOX expression was found in all primary MF (100%) and in a high percentage of AITL (83%)." (PMID 32106280, 2020). "In conclusion, we describe for the first time the expression of TOX in normal tissues and in a large series of B- and T-cell lymphomas." (PMID 32106280, 2020).
Type 2 Diabetes (2 papers, 2015 to 2016). "SNP rs7842858 (8:58987111) resides within TOX, which has been reported to be associated with Type 2 Diabetes in Chinese Han population." (PMID 27701450, 2016).
Aleutian disease (1 paper, 2024). "From this, we identified several candidate genes contributing to the growth and feed efficiency (ARID1B, APPL1, TOX, and GPC5), reproduction (GRM1, RNASE10, WNT3, WNT3A, and WNT9B), pelt quality (MYO10, and LIMS1), and Aleutian disease tests (IFNGR2, APEX1, UBE3A, and STX11)." (PMID 38167844, 2024).
atherosclerosis (1 paper, 2022). A disease characterized by the build-up of fatty material and calcium deposition in the arterial wall resulting in partial or complete occlusion of the arterial lumen. "Various clues suggested that TOX may be involved in atherosclerosis, but its role in ECA has not been reported." (PMID 36140731, 2022).
Atopic Dermatitis (1 paper, 2021). "Surprisingly, we observed higher TOX expression but significantly lower IL-4 expression in Atopic Dermatitis (AD) as a control of a Th2 BID." (PMID 34220814, 2021).
B-cell neoplasm (1 paper, 2020). A group of heterogeneous lymphoid tumors generally expressing one or more B-cell antigens or representing malignant transformations of B-lymphocytes. "TOX was expressed in a large number of B-cell neoplasms, mostly those derived from GC B cells." (PMID 32106280, 2020).
cholangiocarcinoma (1 paper, 2022). A carcinoma that arises from the intrahepatic biliary tree (intrahepatic cholangiocarcinoma) or from the junction, or adjacent to the junction, of the right and left hepatic ducts (hilar cholangiocarcinoma). "Therefore, PD-1 and EOMES represent two independent exhaustion pathways in all three types of cholangiocarcinoma; and other T cell exhaustion markers including LAG3, TIM3, TOX were thus investigated below." (PMID 35346322, 2022).
chronic hepatitis B (1 paper, 2021). "A high dose of Ad-HBV-Luc developed into chronic hepatitis B accompanied by dysfunctional CD8 T cells characterized by high expression of PD1 and TOX and low expression of KLRG1 and GzmB." (PMID 34835079, 2021).
clear cell renal cell carcinoma (1 paper, 2023). "The study aimed to determine the expression of VISTA and TOX within venous tumor thrombus and primary clear cell renal cell carcinoma (ccRCC) and to assess their prognostic value." (PMID 36042047, 2023).
coronary atherosclerosis (1 paper, 2022). Atherosclerosis of the coronary vasculature. "Three significant DEGs—TOX, RasGRP3, and TSPAN13—were selected for IHC analysis based on their high fold changes and possible biological functions in the development of early coronary atherosclerosis to validate the bioinformatics analysis results." (PMID 36140731, 2022).
diabetic nephropathy (1 paper, 2015). "The SNP rs17304270 of the TOX gene gave marginal association with diabetic nephropathy: allele “A”, OR = 1.514 (1.003–2.285), P = 0.047." (PMID 26139146, 2015).
folate deficiency (1 paper, 2023). A nutritional condition produced by a deficiency of FOLIC ACID in the diet. "Indeed, folate deficiency increases the risk of tumor development and the failure of CD8 infiltrates within tumor tissues due to the hypermethylation of TOX and HIF1 genes." (PMID 38375206, 2023).
hepatitis C infection (1 paper, 2022). "We observed that TOX is expressed in HCV-specific CD8+ T cells to a certain degree at each stage of hepatitis C infection." (PMID 35734162, 2022).
inflammatory skin disease (1 paper, 2022). Inflammatory skin disorders covers a broad category that includes many conditions ranging in severity, from mild itching to grave medical health complications These disorders are common in people of all ages and races. "The present study aims to evaluate TOX role of in MF/SS as a possible diagnostic marker by comparing its expression in MF/SS and in inflammatory skin diseases, and to assess whether TOX may also have a prognostic role." (PMID 35885488, 2022).
Insulin resistance (1 paper, 2015). Increased resistance towards insulin, that is, diminished effectiveness of insulin in reducing blood glucose levels. "The biological connections between TOX and T2DM are poorly understood, although TOX gene polymorphisms are associated with insulin resistance traits in both Han Chinese (present study) and European Americans." (PMID 26139146, 2015).
mantle cell lymphoma (1 paper, 2020). Mantle cell lymphoma is a rare form of malignant non-Hodgkin lymphoma affecting B lymphocytes in the lymph nodes in a region called the ``mantle zone''. "Burkitt and mantle cell lymphomas showed TOX expression in a small percentage of cases." (PMID 32106280, 2020).
meningioma (1 paper, 2025). A generally slow growing tumor attached to the dura mater. "Despite this, there was a noted increase in FOXP3 expression in meningioma compared to the control tissues and VS tumours, and genes associated with T cell exhaustion in VS (TOX and TCF7)." (PMID 41437121, 2025).
myeloid leukemia (1 paper, 2021). A clonal proliferation of myeloid cells and their precursors in the bone marrow, peripheral blood, and spleen. "Moreover, TOX has different characteristics in different lymphocytic malignancies, and the role of TOX in T cell exhaustion in patients with myeloid leukemia is worth further investigation." (PMID 33743809, 2021).
myxoma (1 paper, 2024). A benign soft tissue neoplasm characterized by the presence of spindle and stellate cells, lobulated growth pattern, and myxoid stroma formation. "Immune cells surrounding the myxoma displayed suppressive characteristics, potentially contributing to the tumor’s strategy of evading immunity, as evidenced by the impaired effector function of CD8 + T cells expressing GZMK and TOX highly." (PMID 39090109, 2024).
nasopharyngeal carcinoma (1 paper, 2024). A carcinoma arising from the nasopharyngeal epithelium. "We found a mutual positive association between TOX and TOX2, TOX and HAVCR2, and TOX2 and HAVCR2 at the transcriptional level in CD3+ tumor-infiltrating T cells (TILs) in single cell (sc)RNA-sequencing of nasopharyngeal carcinoma samples." (PMID 39080376, 2024).
ovarian tumors (1 paper, 2023). "In our study we showed that HELIOS+ CD8 T cells are present in ovarian tumors and both HELIOS+ and HELIOS- CD8 T cells exhibited high expression of exhaustion marker TOX." (PMID 38187391, 2023).
Pleural effusion (1 paper, 2025). The presence of an excessive amount of fluid in the pleural cavity. "Analysis of DEGs in Cycling GZMA and GZMA CD4 T cells from pleural effusion of HP and LCP revealed that seven transcription factors (MLLT3, KLF12, FOXP1, NFKB1, ZEB2, TOX, JAZF1) were upregulated in both cycling GZMA CD4 and GZMA CD4 cells in MPE of LCP." (PMID 40959273, 2025).
psoriasis (1 paper, 2021). An autoimmune condition characterized by red, well-delineated plaques with silvery scales that are usually on the extensor surfaces and scalp. "TOX and IL-4 expression was significantly higher in the epidermis of CTCL plaques, whereas it was nearly absent in CS or psoriasis." (PMID 34220814, 2021).
pulmonary disease (1 paper, 2025). "Notably, TOX has also been described as an extracellular ligand mediating inflammatory activation through the TOX–RAGE (Receptor for advanced glycation end-products) axis in severe pulmonary disease, highlighting context-dependent roles of this factor." (PMID 41235245, 2025).